TLR7 (toll like receptor 7)
Diseases named in the same sentence as TLR7 in open-access papers (continued):
Sharing a sentence is not in itself a finding about the gene and the disease.
lupus (continued). "The TLR-7 agonist, imiquimod (IMQ), has been frequently used to stimulate disease-mediated activation of this pathway in vivo in preclinical models of lupus and viral-mediated inflammation." (PMID 40574053, 2025). "In lupus-prone mice, TLR9 is essential for the generation of DNA autoantibodies, while TLR7 is crucial for generating antibodies to RNA-containing antigens." (PMID 40584714, 2025). "This interpretation is further supported by our finding that pharmacological blockade of TLR7 with ODN2088 attenuated both presynaptic glutamate release and postsynaptic AMPA receptor activity in superficial dorsal horn neurons of lupus mice." (PMID 41511304, 2025). "Mammalian endosomal TLRs, specifically TLR7, TLR8, TLR9 and TLR3, are crucial in the development of systemic lupus erythematosus (SLE) in humans." (PMID 40976999, 2025). "The B-cell scaffold protein with ankyrin repeats (BANK1) regulates Toll-like receptor-7 (TLR7) signaling in B cells and its absence ameliorates lupus." (PMID 40761803, 2025). "Finally, the TIR domains of TLR7 and TLR9 — which share only 42% sequence identity — could have fundamentally different properties that could encode meaningfully different downstream signaling and, thus, disease outcomes in the context of lupus." (PMID 40794441, 2025). "Similarly, TRIM21, an autoantigen associated with Systemic Lupus Erythematosus (SLE), negatively regulates type I IFN production driven by TLR3, TLR7, and TLR9." (PMID 40495154, 2025). "Plasmacytoid dendritic cells (pDCs) are the dominant acute source of type I IFNs (particularly IFN-α) following endosomal TLR7/9 ligation, and they orchestrate the systemic “IFN-high” endotype seen in lupus and related conditions." (PMID 41153754, 2025). "Compared with healthy men, TLR-7-mediated IFN-α increased in peripheral blood lymphocytes of healthy women, resulting in an increased incidence of female systemic lupus erythematosus." (PMID 39256355, 2024). "Recent research has further demonstrated that inhibitors like TAC5 can selectively target endosomal TLRs (TLR3, TLR7, TLR8, and TLR9) to modulate immune responses and potentially treat autoimmune diseases like psoriasis and systemic lupus erythematosus." (PMID 38732254, 2024). "Therefore, we have now investigated the contribution of endogenous itaconate synthesis to SLE, including its putative role in the development and perpetuation of clinical symptoms and immune dysregulation in the TLR7-induced lupus IMQ model." (PMID 38605883, 2024). "Of particular concern for patients with systemic lupus erythematosus (SLE) is the fact that most SARS-CoV-2 vaccines contain mRNA that could act as a TLR7/8 agonist." (PMID 38833310, 2024). "We used an induced model of murine lupus triggered by epicutaneous administration of the TLR7/8 agonist imiquimod (IMQ) and investigated lupus phenotype in wild type (WT) and Bmal1-myeloid conditional KO mice (Bmal1Mye−/−)." (PMID 39664388, 2024). "Myeloid-conditional Bmal1 knockout mice (Bmal1Mye−/−) and wild type (WT) were treated with epicutaneous TLR7/8 agonist (imiquimod; IMQ) for 6 weeks to induce a lupus phenotype." (PMID 39664388, 2024). "Recent studies used TLR-7 agonists, such as imiquimod (IMQ) or R848, to induce lupus-like conditions in mice, assessing various treatments’ effects on SLE-related pathologies, including hypertension and lupus nephritis." (PMID 39337618, 2024). "Mechanistically, S100A8/9, secreted by lupus MDSCs, enhances IFN-γ production by BMDMs, subsequently promoting TLR7-mediated activation of macrophages and DCs." (PMID 38429401, 2024). "In addition, treatment with SCFAs has been shown to prevent vascular dysfunction and elevated blood pressure (BP) in mice with systemic lupus erythematosus (SLE) induced by imiquimod (IMQ) activation of TLR7." (PMID 39764388, 2024). "In TLR7.tg6.Bank1–/– and IMQ-treated Bank1–/– mice, the frequency of ABCs was significantly reduced compared with Bank1-sufficient lupus-prone mice." (PMID 39163122, 2024).
lupus (continued). "Bank1 deficiency restores the cellular phenotypes of splenic B-lymphocyte populations TLR7.tg6 and IMQ-treated lupus-prone mice." (PMID 39163122, 2024). "Both TLR7 and IFN-I signaling, particularly in myeloid populations, are strong drivers of lupus-like pathology and auto-Ab production in Sle mice." (PMID 36923413, 2023). "This implicates TLR7 and TLR9 signaling in B cells, contributing to autoreactive B cell activation in various lupus mouse models." (PMID 37841260, 2023). "Aberrant TLR7 activation and type 1 IFN expression by pDCs are linked to the pathogenesis of certain types of autoimmune diseases, including systemic lupus erythematosus (SLE)." (PMID 38077311, 2023). "In support of this thesis, the authors cite a case study of a patient with SLE who showed defects in TLR7 and TLR9, which later developed into CVID, resulting in regression of clinical lupus." (PMID 37626865, 2023). "Moreover, chronic TLR7 activation in lupus models is sufficient to cause CD11c+ B cells to differentiate and produce anti-Sm/RNP autoantibodies, whereas B-cell intrinsic TLR7 deficiency reduces the number of CD11c+ B cells and ameliorates lupus-like conditions." (PMID 36875095, 2023). "Currently, a potential relationship between TLR7 stimulation and lupus-like disease development in the imiquimod (IMQ)-induced lupus model is unclear, other than the mechanism involving pDC." (PMID 35371102, 2022). "Several studies have reported increased expression of miR-21 in SLE in response to the activation of the TLR7/type I IFN pathway, a major driver of lupus pathogenesis." (PMID 35499081, 2022). "Inhibitory oligodeoxynucleotides (INH-ODN) can exert an immunomodulatory effect to specifically block TLR7 and TLR9 signaling in systemic lupus erythematosus (SLE)." (PMID 36555668, 2022). "The R-to-H change in NCF1 led to decreased phospholipid-binding affinity, less endosomal localization, and acidified endosomal pH, followed by increased cleavage of TLR7 and TLR9, resulting in excessive activation of pDCs and aggravated lupus progression." (PMID 35788118, 2022). "The TLR7 agonist imiquimod drives lupus nephritis in mice, whereas the pathologies in the lupus-prone strain, New Zealand Black/New Zealand White F1 (NZBWF1) mice, is ameliorated by TLR7 chemical inhibitor or by anti-TLR7 monoclonal antibody." (PMID 35812450, 2022). "We tested the impact of this intervention in two murine models of systemic lupus erythematosus (SLE): a pharmacological model based on chronic epicutaneous application of the Toll-like receptor (TLR)-7 agonist Resiquimod (R848), and 564Igi autoreactive B cell receptor knock-in mice." (PMID 36591222, 2022). "In this paper, when TLR7 or TLR9 was blocked alone, the IRS-661-nanoflower-treated group and the IRS-869-nanoflower-treated group showed better amelioration of lupus symptoms." (PMID 36555668, 2022). "We observed that TLR7 or TLR9 agonists induce higher amounts of MCP-1 and IL-6 on PMs from lupus-prone mice than control mice, confirming that PMs from diseased mice present a more pro-inflammatory phenotype." (PMID 35211864, 2022). "Moreover, TLR8 deletion in the Nba2.Yaa lupus prone mice accelerates SLE due to increased TLR7 responses." (PMID 36389822, 2022). "Despite this mounting link between TLR7 and the pathogenesis of lupus, no human SLE cases due to TLR7 variants have been reported to date." (PMID 35477763, 2022). "Thus, treatment of TLR7/9 inhibitors could be a therapeutic strategy for lupus." (PMID 36555668, 2022). "Moreover, a recent report describes the severe presentation of systemic lupus in a seven-year-old girl with a gain-of-function TLR7 variant who lacked other lupus-predisposing gene alleles, placing TLR7 among the growing list of single-gene causes for lupus, which is typically a polygenic condition." (PMID 35968787, 2022).
lupus (continued). "The genetic analysis detected at least one variant in 11 (26.1%) children, 5 (45.4%) with cSLE (ADAR, TNFAIP3, RNASEH2B, SHOC2, IFIH1) and 6 (54.5%) with lupus-like phenotype (TREX, DNASE1,RNASEH2B, C1S, TLR7, STAT5A, TNFRSF13B)." (PMID 36096831, 2022). "The incidence and course of systemic lupus erythematosus (SLE) differ between the sexes, with a nine-fold higher incidence in women linked to the influence of estrogen on epigenetic, immune and genetic factors (X-linked genes such as Foxp3, TNF and Tlr7)." (PMID 35203537, 2022). "Targeting TLR in SLE may be therapeutically advantageous based on the roles of TLR7 and TLR9 in the effector function of B cells in lupus-like disease and SLE patients as well as the distinctive characteristics of TLR signaling in B cells." (PMID 36439744, 2022). "Irf7 is induced downstream of both Toll-like receptor 7 (TLR7), TLR9, and type I interferon receptor ligation, all key molecules in mouse lupus pathogenesis." (PMID 34220829, 2021). "The present study further investigated the role of MDSC subtypes in disease and found that the percentage of M-MDSCs increased in SLE development, and the activation of TLR7 signal and IFN-α in the lupus microenvironment jointly promoted the differentiation of M-MDSCs." (PMID 34282122, 2021). "In conclusion, overexpression of CTSS in mice influences TLR7 expression, autoantibodies and IFN-α, which leads to an autoimmune reaction and exacerbates lupus-like symptoms." (PMID 34381063, 2021). "A role for IFN-λ in murine SLE was recently reported in a TLR7-induced lupus mouse model." (PMID 34769174, 2021). "Innate stimulation, such as through TLR7 and TLR9, is known to drive activation of autoreactive B cells in systemic lupus erythematosus." (PMID 34234784, 2021). "Our data implies that the modified microbiota has a crucial part in the onset and progression of hypertension and is one of the triggering elements for SLE hypertension, instead of being a result and accompanying phenomenon in the development of lupus after TLR7 activation." (PMID 34573058, 2021). "A series of gene alterations found in these models are deemed to be related to lupus, such as the Fas gene in MRL/lpr and TLR7 in BXSB/Yaa mice." (PMID 34720750, 2021). "Various oligonucleotides that mimic TLR ligands (for TLR7, TLR8, TLR9) have been synthesized and are prospective therapeutics for lupus." (PMID 34572504, 2021). "In pDCs from lupus patients, HCQ was able to decrease type I IFN production, probably preventing the activation of TLR7 and TLR9 receptors." (PMID 33572487, 2021). "The roles of TLR7 and TLR9 in B cells and their crosstalk with BCR ligation have been extensively studied in models for systemic lupus erythematosus (SLE)." (PMID 34293057, 2021). "Antagonists of TLR-7,−8, and−9 inhibit NLRP3 inflammasome-related pathways in NZBW F1 lupus model mice, and therefore represent a potential therapeutic approach for lupus treatment." (PMID 32528469, 2020). "STING has been reported not only to function as a DNA sensor but also to negatively regulate TLR7 and TLR9 responses in lupus-prone mice." (PMID 33093516, 2020). "Another recent study in lupus-prone BXD2 mice supports a link between TR B cell activation and Tlr7 upregulation, driven by endogenous IFN-β production." (PMID 31231380, 2019). "TLR7, found in both mice and humans, recognizes single stranded RNA (ssRNA) and activates Type I interferon (IFN) signaling, a pathway active in many lupus patients." (PMID 31998321, 2019). "Among the MyD88-dependent TLRs—TLR7 and TLR9 are the prominent ones involved in the development of anti-DNA Abs in mouse models of lupus and altered TLR7 and 9 expression has been reported in human SLE patients as well." (PMID 31354738, 2019). "The goal of the present study was to investigate and validate topical TLR7 stimulation as an inducible murine model of lupus-like disease in C57BL/6j (B6) mice, as well as an accelerant in NZM2410 lupus-prone mice." (PMID 31998321, 2019).
lupus (continued). "Ligand to TLR4 or a mixture of ligands to TLR7 and TLR9 were used, based on our prior experience demonstrating additive effect of TLR7 and 9 ligands in unmasking reversible anergy in NZB lupus." (PMID 31632407, 2019). "Signaling through Toll-like receptor 7 (TLR7) drives the production of type I IFN and promotes the activation of autoreactive B cells and is implicated in the pathogenesis of systemic lupus erythematosus (SLE)." (PMID 31231380, 2019). "In contrast, TLR7 was needed for the organomegaly that was observed in TLR9−/− mice, indicating that TLR7 and TLR9 worked together to control clinical symptoms and autoantibody production in lupus." (PMID 30103522, 2018). "E2 also strengthens the amplification of the IFN signature induced by TLR7 and TLR9 stimulation in lupus cDCs." (PMID 29850618, 2018). "Ligation of CD180 inhibits TLR7- and TLR9-mediated activation of macrophages and DCs through the Lyn-SHP-1/2 axis, and subsequently relieves the lupus-symptoms of lupus-prone mice." (PMID 30498494, 2018). "Several murine studies have highlighted the importance of TLR7, and that TLR9 surprisingly provides protection, in lupus pathogenesis." (PMID 30210502, 2018). "In this study, we asked the question if exogenous KKS decreases the IFN responses induced by either TLR (TLR7 and TLR9) or direct IFN-α stimulation in normal and lupus-prone mice, as well as in human PBMCs." (PMID 29456540, 2018). "In CD72−/− mice, Sm/RNP activates B cells reactive to Sm/RNP probably by inducing both BCR signaling and TLR7 signaling, leading to the production of anti-Sm/RNP antibody crucial for development of lupus." (PMID 30333834, 2018). "Toll-like receptor 7 (TLR7) plays an essential role in spontaneous development of GCs and autoimmunity in lupus-prone mice." (PMID 30603051, 2018). "We, and others, have also shown that stimulation via TLR7 and TLR9 is important in the induction of Type I IFNs in lupus." (PMID 29456540, 2018). "In terms of their functions, in lupus-prone mice, TLR7 and TLR9 have opposing roles in inflammation: TLR9 is required for inflammatory regulation but TLR7 promotes lymphocytes activation and serum IgG production." (PMID 30131810, 2018). "As we found increased TLR7 co-localization with Rab7 and LAMP1 in pDCs from patients with SLE, the IRF signaling pathway appeared to be more active in lupus pDCs." (PMID 29052537, 2017). "Furthermore, augmented TLR7 expression is observed in cancer and autoimmune diseases such as rheumatoid arthritis and systemic lupus erythematosus (SLE)." (PMID 28928743, 2017). "While TLR7 promotes cDC activation in lupus, TLR8 downregulates TLR7 expression and TLR7-dependent cDC activation." (PMID 27034965, 2016). "In the tape-stripping model, depletion of pDCs protected NZB/W F1 mice from developing chronic skin lesions and so did the treatment of TLR7 and TLR9 inhibitors, suggesting that TLR7 and TLR9 signaling is important for lupus development." (PMID 27509492, 2016). "We examined the role of TLR7 in generating anti-U1A PB and PC from CD19+CD138−IgD−IgM− switched memory-like B cells in pristane-induced lupus." (PMID 26717913, 2015). "Antimalarial drugs such as hydroxychloroquine which act as a TLR7, TLR8 and TLR9 antagonist are used for the treatments of rheumatoid arthritis and systemic lupus erythematosus." (PMID 26226614, 2015). "Accelerated lupus pathogenesis in TLR9−/− C57 background mice was reported, in which mild ANA production with overactivated TLR7 signal in TLR9−/− B cells is observed." (PMID 26068236, 2015). "Activation of TLR7 and TLR9 by endogenous RNA- or DNA-containing ligands, respectively, is thought to contribute to the complicated pathophysiology of systemic lupus erythematosus (SLE)." (PMID 25695778, 2015).
lupus (continued). "Dynavax Technologies in partnership with GlaxoSmithKline have consequently developed DV1179, a bifunctional inhibitor of TLR7 and TLR9, which has been shown to reverse glucocorticoid resistance in both human cells and animal models of lupus." (PMID 24474949, 2014). "Moreover, a link between TLR7 gene dosage and increased autoimmunity has been identified in a mouse model of systemic lupus erythematosus (SLE); however, the effects of varying TLR7 CN on SLE were inconsistent." (PMID 24517461, 2014). "TLR7 and TLR9 expression levels are significantly elevated in glomerulonephritis in systemic lupus erythematosus." (PMID 24810370, 2014). "Systemic lupus erythematosus (SLE) is a debilitating autoimmune disease contributed to by excessive innate immune activation involving toll-like receptors (TLRs, particularly TLR7/8/9) and type I interferon (IFN) signaling pathways." (PMID 23468661, 2013). "More recently it has been shown that exogenously administered agonists of TLR3, TLR7 and TLR9 can exacerbate murine lupus." (PMID 24086313, 2013). "Interestingly, TLR deficiency differentially affects lupus-specific autoantibody production, with absence of TLR7 or TLR9 reducing anti-ribonucleoprotein responses but not anti-DNA whereas lack of TLR4 reduced production of both anti-ribonucleoprotein and anti-DNA autoantibodies." (PMID 23557436, 2013). "Frequencies of TLR7-expressing precursor of myeloid dendritic cells (pre-mDCs) and mDCs in 28 AOSD patients, 28 patients with systemic lupus erythematosus (SLE) and 12 healthy controls (HC) were determined by flow cytometry analysis." (PMID 23497717, 2013). "Further, the type of viral latency cells with high TLR7, IRF-5, and IRF7 (type III) are probably present in lupus patients in vivo." (PMID 22952664, 2012). "In particular, immune complexes containing the lupus autoantigen U1snRNP or nucleosomes activate DCs and autoreactive B-cells via TLR7 and TLR9, respectively, contributing in this way to pathogenesis of systemic lupus erythematosus." (PMID 23112799, 2012). "Recognition of self-nucleic acids by TLR7 and TLR9 on plasmacytoid dendritic cells is considered to be a key steps in IFN production in lupus and correlated with the severity of disease." (PMID 22952664, 2012). "It has become evident that RNA- and DNA-containing immune complexes, which often exist in sera of patients with systemic lupus erythematosus (SLE), can activate TLR7 and TLR9 signaling." (PMID 21396113, 2011). "This is relevant because DNA and RNA in the major lupus autoantigens, nucleosomes and RNP, can stimulate APCs via TLR-9 and TLR-7 pathways, respectively." (PMID 19405952, 2009). "Moreover, refinement of the palindromic structure to generate combined selective TLR7/TLR9 inhibitors together with anti-B-cell-depleting protocols to re-establish critical B-cell differentiation checkpoints may result in better treatments for human lupus." (PMID 19476613, 2009). "Another study showed that a dual inhibitor of TLR7 and 9, immunoregulatory sequence (IRS) 954, can prevent progression of disease when injected in the lupus prone (NZB×NZW)F1 mice." (PMID 18652679, 2008). "However, in lupus models, FDCs capture and retain self-antigens via CD21, activating type I IFN production in a TLR7/IRF5-dependent manner, thereby promoting GC responses and pathogenic autoantibody production." (PMID 40721841, 2025). "We inserted the chimeric TLRs into the endogenous locus of TLR7 and TLR9, respectively, in lupus-prone MRL/lpr mice and then studied signaling, TLR ligand-inducible gene expression, TLR localization, and, finally, the effect of the TIR domain swaps on lupus-like disease." (PMID 40794441, 2025). "Cinnamon has been proven to modulate intestinal barrier function, neuroinflammation, and many autoimmunity pathways, particularly TLR2 and TLR4, but it has never been tested in TLR7-induced diseases, including in an experimental lupus model." (PMID 40507090, 2025).